MYC (MYC proto-oncogene, bHLH transcription factor)
Diseases named in the same sentence as MYC in open-access papers (continued):
Sharing a sentence is not in itself a finding about the gene and the disease.
cancer (continued). "Although various cancer types, including many G3 MB tumors, exhibit aberrantly high MYC abundance, clinical targeting of MYC has remained elusive." (PMID 37130865, 2023). "Expression of these genes occurs in many cancer-promoting pathways including MYC, hypoxia, biosynthesis (ribosomal subunits) and catabolism (proteasome subunits and essential autophagy genes)." (PMID 36575316, 2023). "Other studies examining the programs of splicing regulation in cancer have also identified HRAS as a MYC-dependent exon." (PMID 37399401, 2023). "MYC’s ubiquitous functions and disordered structure have limited our ability to effectively target this oncogene for cancer therapy, which has led to it being branded as ‘undruggable’11." (PMID 37130865, 2023). "We find that SCARB2 regulates cancer stem cell-like properties of HCC by enhancing MYC activity, which plays important role in promoting HCC initiation and progression." (PMID 37739936, 2023). "The transcription factor MYC plays an important role in regulating the bioactivity of cancer stem cells." (PMID 36966168, 2023). "Pan-cancer analyses have shown that MYC is the 3rd most frequently amplified gene in malignant neoplasms, and its alterations are mutually exclusive with other genetic drivers like PIK3CA, PTEN, APC or BRAF." (PMID 37443779, 2023). "These DUBs (USP22, USP28, USP29, USP36, USP37 and OTUD6A) are observed in stabilizing MYC in cancer cells." (PMID 36765885, 2023). "In particular, MYC has been shown to play an important role in regulating metabolic reprogramming in normal development and cancer." (PMID 36609617, 2023). "Our bioinformatic analysis unexpectedly identified MYC signaling as an alternative pathway for cancer cell proliferation upon the knockdown of both MYB and NOTCH1." (PMID 36879115, 2023). "The oncogenic miRNAs activated by MYC are involved in the initiation and progression of MYC-driven cancers." (PMID 37430087, 2023). "First, the subinteractomes of these ORF proteins contain proteins associated with ‘cancer hallmark’ and oncoproteins (e.g., the case of C5orf24 and its protein partners XPO1, PBX1, MYC, CIC, GOPC, CREB1 and STK11)." (PMID 37373333, 2023). "Because NHP2 is essential, MYC-tagged wild-type NHP2 (NHP2-WT) or mutant NHP2 (NHP2-A39T or NHP2-T44M) were expressed in telomerase-positive HeLa cancer cell line first, and then the bulk endogenous NHP2 was targeted with CRISPR/Cas9." (PMID 37440454, 2023). "The MYC family oncoproteins, particularly c-MYC, are essential master regulators of metabolic reprogramming in a variety of cancer types, including ovarian cancer." (PMID 36765581, 2023). "Nevertheless, all of the inhibitors against SP1, HIF1A, or MYC can be considered potential anticancer drugs due to the nature of these TFs as master regulators of cancer." (PMID 37998757, 2023). "MYC is typically found deregulated in human cancers, for instance, following gene amplification or alterations in upstream pathways controlling MYC protein expression, turnover, or stability." (PMID 36765784, 2023). "MYC promotes cancer initiation and maintenance by regulating multiple biological processes, such as proliferation and stem cell function." (PMID 37400551, 2023). "MYC can regulate PD-L1 through either direct binding to its promoter or through post-transcriptional mechanisms in multiple types of cancers." (PMID 37601651, 2023). "Another approach being studied aims to target the expression of c-MYC in cancer cells via the stabilization of the G4 structures present in its promoter region." (PMID 36979947, 2023). "Alternatively, while cancer cells are distal from the oxygen source, MYC, in cooperation with HIF-1α can suppress mitochondrial respiration without affecting the mitochondrial biogenesis process." (PMID 37762231, 2023). "c-Myc is overexpressed in approximately 70% cancers, 20% of which show MYC amplification or translocation." (PMID 37573463, 2023).
cancer (continued). "A well-defined source of circadian disruption in cancer is amplification of the MYC oncogene or its closely related paralogue MYCN (N-MYC), which leads to overexpression of MYC or N-MYC." (PMID 37639465, 2023). "In vitro drug sensitivity testing using an established SCCC organoid revealed that among the two therapeutic targets of precision medicine identified, the KRAS pathway inhibitor exerted adequate anti‐cancer effects compared to the MYC inhibitor." (PMID 36691316, 2023). "In particular, we prioritized an oncogenic RBP-HNRNPK, which potentially interacts with MYC to promote cancer cell proliferation, migration, and invasion." (PMID 36681772, 2023). "The fundamental role of EBTFs in cancer has been highlighted by studies on the canonical oncogene MYC, yet many EBTFs exhibit common features, implying the existence of shared molecular principles of how they are involved in tumorigenesis." (PMID 37601651, 2023). "The top Cancer Hallmark pathways suppressed in the SI were oxidative phosphorylation (OXPHOS), MYC targets VI and V2, E2F targets, and the G2M checkpoint." (PMID 36980301, 2023). "We find that KCNQ activity impacts cancer cell growth through activating β-catenin and MYC via the modulation of cadherin junctions and that already clinically available drugs that interact with KCNQ channels are a promising therapeutic avenue for GOA." (PMID 37748809, 2023). "Up-regulation of MYC is considered a driver for the onset and progression of many human cancers, including Group 3 MB." (PMID 37599362, 2023). "The oncogene MYC, a basic helix-loop-helix (bHLH) transcription factor, play a critical role in regulating various cancer cellular functions, including promoting proliferation, metastasis, stemness and drug resistance." (PMID 36765885, 2023). "In this review we include the metabolism of polyamine, the regulation of polyamine metabolism by MYC signaling, the utility of polyamine as therapeutic targets and cancer biomarkers." (PMID 36765581, 2023). "By addressing these objectives, we aim to contribute to the growing body of knowledge surrounding MYC-driven oncogenesis and its implications for cancer treatment." (PMID 37755397, 2023). "Although targeting c-MYC is challenging, numerous investigations demonstrated the potential significance of c-MYC inhibition for cancer therapy." (PMID 37627164, 2023). "According to our study, co‐targeting of the MYC protein with small molecules or genetic knockdown approaches targeting members of these proteins results in cancer cell apoptosis." (PMID 36639831, 2023). "MYC can provide an advantage to cancer cells by promoting proliferation and angiogenesis, helping to evade the immune response." (PMID 37173935, 2023). "Correspondingly, our analyses of human cancer cell line and patient data demonstrated that MYC amplification and high MYC expression prior to mTORi treatment are associated with poor mTORi response." (PMID 37642941, 2023). "This intricate interaction between eccDNA, MYC, and miRNAs provides a comprehensive view of the complex gene regulatory networks in cancer cells and underscores potential targets for more effective therapeutic interventions." (PMID 39534571, 2023). "Another example is the targeting of oncogenic transcription factor MYC that regulates gene expression, is involved in cancer cell transformation and growth, and whose overexpression is the most common driver of cancer." (PMID 36855776, 2023). "The MYC oncogene is a grand orchestrator of cancer growth and immune evasion, and it can regulate the TME by affecting both innate and adaptive immune effector cells and immune regulatory cytokines." (PMID 37448185, 2023). "Overexpression of Omomyc inhibits MYC-mediated transcription and MYC-dependent cell transformation and offers promising therapeutic impact in several cancer mouse models." (PMID 36969025, 2023).
cancer (continued). "Uncovering the central role of MYC as a regulator of both catabolism and anabolism started with studies on cancer cells in the mid-1980s." (PMID 37731815, 2023). "MYC’s role in cancer stem cells is unique as it can perpetuate stemness and drive malignancy, both important phenotypes in cancer stem cells." (PMID 37370820, 2023). "As Omomyc represents a new clinical modality to target MYC, a most wanted target found deregulated in the majority of human cancers, our findings provide grounds to support the administration regimen in solid tumors." (PMID 36765784, 2023). "MYCL is a member of the MYC proto-oncogene family and regulates cellular programs orchestrating multiple hallmarks of cancer, including proliferation, metabolism, invasiveness, and immune surveillance." (PMID 37897503, 2023). "Since the MYC promoter is frequently overactivated in many cancer types, interference with MYC mRNA transcription by stabilizing transcription-inhibitory secondary DNA structures has become an option to silence MYC expression." (PMID 36969025, 2023). "On the other hand, as indicated in Section 2, the paired expressions of uPAR and some specific cancer driver genes (i.e., MYC and SMAD4) can be utilized to further differentiate drug effects for precise medication to revert cancerous phenotypic change." (PMID 37895906, 2023). "Together, our findings suggest that KDM4B silencing suppresses cancer cell survival, proliferation, migration, and invasion through the MYC signaling pathway." (PMID 38093312, 2023). "The answer to this question would explain how MYC shifts the behavior of cells by disrupting their molecular clock and circadian rhythmicity, and begin to explain what benefit MYC-amplified cancers gain from disruption of the molecular circadian clock." (PMID 37639465, 2023). "It is noteworthy that these findings were determined in cancer cells with relatively low MYC levels and intact circadian rhythms." (PMID 37601651, 2023). "It is common for MYC, a cancer-promoting oncogene, to be activated and expressed abnormally in various cancers." (PMID 36624401, 2023). "Most commonly, MYC proto-oncogenes are overexpressed in cancer patients and have been intensively investigated as potential targets of cancer treatment." (PMID 37444499, 2023). "The interaction effects between circREOS and HuR in regulating the expression of MYC and cancer progression in OS cells was further investigated." (PMID 37151387, 2023). "MYC also promotes aerobic glycolysis in cancer cells and activates glutamate biosynthesis from glutamine, which provides the required energy and substrate." (PMID 36769322, 2023). "The c-MYC proto-oncogene is commonly amplified in human cancer, with ∼50% of all cancers displaying elevated expression of c-MYC." (PMID 36719686, 2023). "This indicates that HIF-1 and SP1 can cooperatively activate cancer-related cellular mechanisms while the relationship between HIF-1 and MYC regarding the regulation of cancer-related cellular mechanisms can be variable depending on the context." (PMID 37998757, 2023). "DHODH inhibitors suppress MYC expression, presumably due to the induction of apoptosis and cell cycle arrest in cancer cells." (PMID 36814599, 2023). "Both USP28 and USP36 can bind to c-MYC in cells, and deubiquitinize c-MYC, thereby modulating cancer cell growth and apoptosis." (PMID 37251574, 2023). "The Myc family of transcription factors is composed of c-MYC, N-MYC and L-MYC whose expression is dysregulated in over 70% of human cancers and associated with poor prognosis." (PMID 38078012, 2023). "This compound increased the melting temperature of c-MYC G4 by more than 6 °C in a CD study and it can induce cancer cell apoptosis in a dose-dependent manner." (PMID 36979947, 2023). "The expression levels of genes involved in cancer invasiveness (MYC, VEGFB, IL33, PTGS2, and PTGER2) were increased." (PMID 37601099, 2023).
cancer (continued). "Resistance to mTORi has previously been investigated in several cancer types, and MYC has been reported as a resistance mechanism." (PMID 37642941, 2023). "For example, the decrease in let‐7 miRNAs, found in many cancers, results in overexpression of their oncogenic targets such as MYC, RAS, HMGA2, BLIMP1, among others." (PMID 37042179, 2023). "These cancer cell lines are an extremely useful model to study the effect of MYC at the molecular layer which, through the execution of deregulated gene expression programs, consequently impacts cell behavior." (PMID 36830948, 2023). "In this study, using the newly defined modules as analytical tools, we observed that at least the CORE and PAF modules, as well as the MYC module were all shared by ESCs and cancer cells." (PMID 37059858, 2023). "It is interesting to note that one of the most dysregulated TFs by HIF1A-As2 KD is MYC, an important oncogene that modulates cell proliferation, cell cycle and apoptosis in cancer." (PMID 37041291, 2023). "These functions are especially critical for highly proliferating cancer cells and, indeed, pro-oncogenic growth promoting factors, such as MYC and mTORC1, incorporate regulation of one-carbon metabolism genes as part of their transcriptional signature." (PMID 37949226, 2023). "In fact, the deregulation of MYC gene and concomitantly of multiple MYC targets is a frequent event in tumorigenesis occurring in approximately 70% of all human cancer cell types, indicating that aberrant MYC expression drives the genesis of many tumors." (PMID 36969025, 2023). "A good example of this is the Yamanaka factor MYC, which is a well-known oncogene and accounts for a great deal of transcriptional similarity between iPSCs and cancer cells." (PMID 37515162, 2023). "Nowadays, multiple organic compounds, nucleic acids, or peptides specifically interfering with MYC activities are in preclinical or early-stage clinical studies, but none of them have been approved so far for the pharmacological treatment of cancer patients." (PMID 36969025, 2023). "Brd4 has attracted enormous attention as a promising molecular target for cancer therapy in recent years because pharmacological inactivation of Brd4 was shown to remarkably suppress expression of the MYC oncogene." (PMID 37049806, 2023). "The TCGA ATAC-seq study performed by the laboratory of Howard Chang similarly noted different open chromatin patterns at the MYC locus in different cancers." (PMID 37415185, 2023). "For example, a “cancer zone” has been defined as a range of MYC (and/or E2F) expression where a slight increase is associated with carcinogenesis but a further increase would lead to cell death, incurring into an error threshold in cancer evolution." (PMID 37987212, 2023). "Omomyc constrains MYC activity in cancer cells and in vivo models by directly affecting MYC binding to DNA and MYC protein–protein interactions, as shown by our previous works." (PMID 36830948, 2023). "Observations from cancer cells that MYC-driven excessive anabolic metabolism can trigger ISR brings additional complexity into decoding ATF4- and MYC-driven transcriptional responses." (PMID 37731815, 2023). "MYC contributes to several hallmarks of cancer, including the escape from programmed cell death, promoting sustainable proliferation, genome instability, escape from immunosurveillance, and change of cellular metabolism." (PMID 37570631, 2023). "In detail, MYC alters genomic enhancer and super-enhancers of transcription that are frequently deregulated in cancer." (PMID 38023987, 2023). "The prevalence of deregulated MYC expression in diverse cancer types suggests that heightened MYC activity contributes to the pathogenesis of most, if not all, cancers." (PMID 37400551, 2023). "This identified a program of 1,039 cassette exons whose splicing correlated with MYC signaling during cancer progression." (PMID 37399401, 2023).
cancer (continued). "MYC is directly involved in suppressing cancer cell migration and invasion by transcriptional and translational suppression of target genes in a TGF-beta antagonistic manner." (PMID 37347737, 2023). "As shown in t-SNE plots and violin plots, among the major cell types, MYC was mainly expressed in malignant tumor cells, osteoblasts and fibroblasts." (PMID 37055822, 2023). "MYC is a transcription factor regulating groups of genes (MYC targets) related to enhance cell growth in most types of human cancers." (PMID 36874096, 2023). "The accumulated lactate is toxic to the cell, but through the activation of monocarboxylate transporters (MCT1 and MCT2) by MYC, cancer cells can reduce its intracellular level." (PMID 37443779, 2023). "Kim et al7 found that only the MYC module accounts for the similarity of transcriptional programs between ESCs and cancer cells." (PMID 37059858, 2023). "The transcription factor MYC (or c-MYC) is a major regulator of metabolic rewiring in cancer, stimulating glycolysis, nucleotide biosynthesis, and glutamine utilization, which are known or predicted to be affected also in mitochondrial diseases." (PMID 37731815, 2023). "Mechanically, MINCR acts an oncogene in cancers via regulating MYC, targeting miRNAs, and mediating Wnt/β-catenin signaling pathways." (PMID 37215074, 2023). "One of the potential ways to treat cancer is to inhibit MYC expression; however, owing to the disorderly structure of the MYC protein, there is currently no small-molecule inhibitor with good activity and high selectivity that directly targets MYC." (PMID 36918935, 2023). "Further research and development in this field are essential for advancing our understanding and therapeutic targeting of MYC in cancer treatment." (PMID 37755397, 2023). "Additional studies are necessary to further define the context of MYC and maintenance of the core circadian clock in tumors that are believed to be driven largely by the cancer stem cell compartment." (PMID 37639465, 2023). "We propose that ZINC15675948 is a promising natural product-derived compound targeting c-MYC in c-MYC-driven cancers through DNA damage, cell cycle arrest, and apoptosis." (PMID 37570631, 2023). "Among the four BET proteins, Brd4 is known to be highly enriched in super-enhancers that promote the expression of factors including c-MYC to support cancer growth and development." (PMID 37049806, 2023). "MYC is involved broadly in many cancer types and its expression was estimated to be deregulated in up to 70% of human cancers." (PMID 37193964, 2023). "The alteration of MNX1-AS1 at 7q36, both via amplification and MYC-induced transcriptional activation, is one of the most common aberrations in several cancers, including non-small cell lung cancer (NSCLC) and CRC." (PMID 37443779, 2023). "Inhibiting BRD4 has been proven to be effective in treating malignant tumors with pathological activation of c-MYC." (PMID 37446009, 2023). "CIP2A regulates PP2A and subsequently downstream effects on PLK1, E2F1, Akt, DAPK1, and c-MYC in multiple types of cancer." (PMID 37763671, 2023). "The thiomyristoyl lysine compound (TM) was proven to be a highly potent and specific SIRT2 inhibitor in several cancer types, promoting MYC ubiquitination and degradation, among others." (PMID 37443779, 2023). "For instance, a study in TNBC identified that TXNIP suppression by MYC can reprogramme the metabolic phenotype of cancer cells." (PMID 37794178, 2023). "MYC activity has been shown to either promote apoptosis or survival of cancer cells in response to an anti-mitotic agent." (PMID 37345125, 2023). "The repression of c-MYC is one important task in the therapy of many cancer types, including in colorectal cancer." (PMID 37190100, 2023).